PCSK9 (proprotein convertase subtilisin/kexin type 9)
Diseases named in the same sentence as PCSK9 in open-access papers (continued):
Sharing a sentence is not in itself a finding about the gene and the disease.
neuropathy (4 papers, 2023 to 2025). A disorder affecting the nervous system that manifests with pain, tingling, numbness, and/or muscle weakness. "This review integrates current evidence on PCSK9 biology across neural compartments, highlights mechanistic links to Schwann cell lipid handling, and outlines research priorities to resolve neural safety and therapeutic potential in lipid-driven neuropathies." (PMID 41002444, 2025). "Knockout of Pcsk9 might reduce thermal and mechanical pain sensitivity and neuropathy in mice." (PMID 40823647, 2025). "Clinically, large trials of PCSK9 inhibitors are broadly reassuring for brain safety, yet they were not built to detect small-fiber change, so neuropathy questions need targeted endpoints." (PMID 41002444, 2025).
non-alcoholic steatohepatitis (4 papers, 2019 to 2025). "PCSK9’s role in alcoholic versus non-alcoholic steatohepatitis might differ and needs further exploration." (PMID 31748600, 2019).
skin cutaneous melanoma (4 papers, 2023 to 2024). "Current studies also highlight the potential of curcumin in inhibiting PCSK9’s effect on cutaneous melanoma by regulating oxidative stress-related signaling pathways." (PMID 38760735, 2024). "The main discovery of this study is that PCSK9 may serve as a potential therapeutic target for skin melanoma." (PMID 38760735, 2024).
ST Elevation Myocardial Infarction (4 papers, 2019 to 2025). A myocardial infarction that produces elevation in the ST segments of the ECG. "Separate findings from another study of 126 patients with ST-elevation myocardial infarction (STEMI) demonstrated the prognostic relevance of the ratio of circulating fc-PCSK9 to mature-PCSK9 48 h after a percutaneous intervention procedure." (PMID 39273186, 2024). "Interestingly, in line with our preclinical findings, an inverse correlation between baseline levels of SIRT1 and PCSK9 was observed (R = −0.1753, P = 0.0262) which was particularly pronounced in patients with ST-elevation myocardial infarction (r = −0.2306, P = 0.0297)." (PMID 40653676, 2025).
systemic inflammatory response syndrome (4 papers, 2022 to 2024). SIRS is a serious condition related to systemic inflammation, organ dysfunction, and organ failure. "So, PCSK9 can be used as a prognostic biomarker for early prediction of organ dysfunction and mortality risk in pediatric sepsis syndrome." (PMID 38972879, 2024).
Abdominal obesity (3 papers, 2021 to 2023). Excessive fat around the stomach and abdomen. "Moreover, a study on subjects with abdominal obesity showed that a n-6 PUFA-rich diet reduced plasma levels of proprotein convertase subtilisin/kexin type 9 (PCSK9) compared with SFA intake." (PMID 36901998, 2023).
alcohol (3 papers, 2019 to 2025). "They presented 2 mutations in the PCSK9 gene, which encodes proprotein convertase subtilisin/kexin type 9, that are implicated in the etiology of alcohol dependence and harm." (PMID 41204494, 2025). "We demonstrated that chronic anti-PCSK9 treatment using the monoclonal antibody alirocumab attenuated alcohol-induced steatohepatitis in the rat model." (PMID 31748600, 2019). "Although it remains unclear whether the protective effects of alirocumab on alcohol-induced liver injury are primarily related to LDL regulation, anti-inflammatory actions, or both, anti-PCSK9 treatment might represent a novel approach to target several domains of ALD and AUD." (PMID 31748600, 2019).
allergic disease (3 papers, 2022 to 2025). An immune response that occurs following re-exposure to an innocuous antigen, and that requires the presence of existing antibodies against that antigen. "Although our study also detected associations between PCSK9 inhibitors and other allergic diseases (a protective role in AD, but a harmful effect on AR), these were not consistently reflected across both methods." (PMID 38623319, 2024). "First, a detailed inquiry into the patient’s history of gastrointestinal surgery and allergies should be conducted before initiating biologic agents such as PCSK9 inhibitors, in order to identify individuals at potential high risk." (PMID 41431087, 2025).
anaphylaxis (3 papers, 2018 to 2025). An acute hypersensitivity reaction that occurs from exposure to an allergen. "The immunogenic effects of the PCSK9 inhibitors varying from mild injection site reactions to anaphylaxis and loss of drug efficacy need to be scrutinized further." (PMID 29850255, 2018). "Therefore, our pharmacovigilance study assessed the association between reporting of PCSK9 inhibitors and hypersensitivity or anaphylaxis." (PMID 41266479, 2025). "Among all reports in FAERS during the study period involving PCSK9 inhibitors, we identified 12,591 cases of hypersensitivity and 17,214 cases of anaphylaxis." (PMID 41266479, 2025).
ankylosing spondylitis (3 papers, 2021 to 2024). An autoimmune chronic inflammatory disorder characterized by inflammation in the vertebral joints of the spine and sacroiliac joints. "Our previous study reveals that proprotein convertase subtilisin/kexin type 9 (PCSK9) is positively related to inflammatory markers, T helper (Th)‐17 cells, and treatment response in ankylosing spondylitis (AS) patients." (PMID 37249282, 2023). "The lack of a significant association with PCSK9 score, NPC1L1 score and LDL polygenetic score may imply that simply lowering serum cholesterol levels would be unlikely to contribute to the prevention of ankylosing spondylitis." (PMID 34692687, 2021).
Aortic dissection (3 papers, 2019 to 2023). Aortic dissection refers to a tear in the intimal layer of the aorta causing a separation between the intima and the medial layers of the aorta. "Many genes, such as YAP1, Sirtuin-1, PCSK9, polycystin-1, and brahma-related gene 1, have also been reported to be associated with the pathophysiologic processes of aortic dissection by influencing the proliferation and migration of VSMCs." (PMID 31751374, 2019).
aortic valve disease (3 papers, 2014 to 2026). "It is not known whether aortic valve disease elevates plasma PCSK9 levels." (PMID 25180781, 2014).
aortic valve stenosis (3 papers, 2021 to 2025). Aortic valve stenosis (AVS) is a condition characterized by narrowing of the heart's aortic valve opening. "This is because the PCSK9 R46L loss-of-function mutations, which cause reduced exposure to these lipoproteins, are associated with a reduced risk of aortic valve stenosis." (PMID 35890111, 2022). "However, PCSK9 inhibition therapy to reduce aortic valve stenosis progression is still to be researched." (PMID 35890111, 2022).
Arterial thrombosis (3 papers, 2021 to 2023). The formation of a blood clot inside an artery. "PCSK9 enhances platelet responsiveness and arterial thrombosis and it is considered as a danger-associated molecular pattern, similar to oxLDL, advanced glycated -proteins, S100A, and cell-derived microvesicles." (PMID 35071356, 2021). "It was observed that PCSK9 knockout mice have reduced platelet activity and developed less agonist-induced arterial thrombosis compared to the animal control group." (PMID 37111513, 2023). "Qi and colleagues found that PCSK9 inhibition was able to counteract arterial thrombosis in individuals with elevated levels of PCSK9 that were related to genetic or acquired causes." (PMID 35806921, 2022).
astrocytoma (3 papers, 2020 to 2024). "In human astrocytoma cells, PCSK9 reduced cholesterol content (−20%; p < 0.05), with a greater effect in presence of beta amyloid peptide (Aβ) (−37%; p < 0.01)." (PMID 36293049, 2022).
breast disease (3 papers, 2022 to 2024). "The observation of a significant association between severity of breast disease and PCSK9 levels points toward a potentially important effect of PCSK9 in cancer, the mechanism of which deserves to be further investigated." (PMID 36203122, 2022). "While such a merge of non-cancerous samples with early-stage cancerous samples to form a control group may have blurred associations between PCSK9 and breast disease severity, a statistically significant association was obtained once samples were stratified according to breast disease severity." (PMID 36203122, 2022). "In summary, in this small cohort of 46 women, PCSK9 levels tended to increase with the severity of the breast disease." (PMID 36203122, 2022). "A significant positive correlation appeared between PCSK9 levels and the severity of the breast disease (Rho Spearman = 0.34, p = 0.02), a similar correlation as the one obtained before any adjustment (Rho Spearman = 0.34, p = 0.02)." (PMID 36203122, 2022). "The main finding of this study is that PCSK9 levels tend to increase along with breast disease severity, a finding that warrants confirmation in a larger cohort." (PMID 36203122, 2022). "Next, we investigated the relationship between severity of breast disease and the lipid profile, PCSK9, ANGPTL3 and Lp(a) plasma levels, adjusted for age and BMI." (PMID 36203122, 2022). "In this small cohort of 46 women, PCSK9 levels tended to increase with the severity of the breast disease." (PMID 36203122, 2022). "A near-significant increase in PCSK9 levels was obtained with breast disease severity (p= 0.056)." (PMID 36203122, 2022). "Moreover, PCSK9 levels positively correlated with breast disease severity (benign, stage 0, stage III) (Rho = 0.34, p < 0.05, n = 46)." (PMID 36203122, 2022). "In the present study, we investigated the levels of PCSK9, ANGPTL3 and Lp(a) in women with breast diseases of increasing severity (benign, stage 0 and stage III cancers)." (PMID 36203122, 2022). "The increase in PCSK9 with breast disease severity could be observed by chance rather than reflect a real difference in PCSK9 levels (Type 1 error, rejecting the null hypothesis)." (PMID 36203122, 2022).
Cerebral ischemia (3 papers, 2022 to 2024). Restriction of arterial blood supply to the brain associated with insufficient oxygenation to support the metabolic requirements of the tissue. "In supporting that, in a rat model of cerebral ischemia PCSK9 inhibition reversed the release of inflammatory cytokines induced by Toll-like receptor 4 (TLR4) and NF-κB activation." (PMID 39769398, 2024).
cholestasis (3 papers, 2017 to 2025). Impairment of the bile flow caused by obstruction within the liver, or outside the liver in the bile duct system. "Thus, the aim of the present study was to assess the associations between PCSK9, liver synthesis, cholestasis, and mortality." (PMID 28727814, 2017). "Across all cases, hepatocellular PCSK9 protein level was increased in the presence of cholestasis and positively correlated with hepatic SREBP-2 expression." (PMID 41233786, 2025). "PCSK9 protein levels were also increased in our septic patients with cholestasis, though this effect was marginal." (PMID 41233786, 2025). "Patients with almost normal aminotransferase and cholestasis marker levels (n = 47) had significantly higher PCSK9 levels than controls." (PMID 41271978, 2025). "The parameters of cholestasis and hepatic detoxification (total bilirubin, conjugated bilirubin, and unconjugated bilirubin) were negatively correlated with PCSK9 serum concentrations." (PMID 28727814, 2017). "However, in the entire cohort, patients with cholestasis had higher levels of hepatocyte PCSK9 (p = 0.049)." (PMID 41233786, 2025). "PCSK9 was negatively correlated with markers of liver function and cholestasis (INR, bilirubin)." (PMID 28727814, 2017). "Analysis of the correlation of PCSK9 with liver synthesis parameters, cholestasis, and other mortality-related parameters (i.e., MELD scores) was performed and revealed significant correlations between PCSK9 and the markers of liver function." (PMID 28727814, 2017). "In addition, with decreasing PCSK9 levels, those of γ-glutamyl transferase decreased significantly, providing no support for a link between PCSK9 levels in blood and cholestasis in these patients." (PMID 28727814, 2017).
chronic hepatitis (3 papers, 2020 to 2023). An active inflammatory process affecting the liver for more than six months. "Considering the PCSK9 levels in each subgroup, we observed a significant increase in its levels in chronic hepatitis HCV positive (HCV+) compared to controls." (PMID 32998342, 2020).
colitis (3 papers, 2023 to 2025). Inflammation of the colon. "An adenovirus-mediated experimental approach to block colonic PCSK9 improved inflammation and colitis severity in rats, suggesting a functional link between high PCSK9 protein levels in the colon of these animals and disease severity." (PMID 40265438, 2025). "The authors documented that PCSK9 inhibition suppressed the activation of TLR4/NF-κB in a rat model of colitis." (PMID 39982361, 2025). "The PCSK9 inhibitor could inhibit the activity of TLR4/NF-κB to ameliorate colitis induced by 2,4,6-trinitrobenzene sulfonic acid." (PMID 37350960, 2023).
colon adenocarcinoma (3 papers, 2022 to 2025). "After that, we analyzed PCSK9 level using the TCGA data (which included 41 normal tissues and 286 colon adenocarcinoma tissues) and found that PCSK9 expression was significantly higher in the primary tumor samples than that in the normal tissues, which is consistent with our conclusion." (PMID 36242053, 2022).
dermatitis (3 papers, 2020 to 2024). An inflammatory process affecting the skin. "To date, reports regarding the effect of PCSK9 inhibition on skin inflammation have been conflicting." (PMID 35862195, 2022).
epilepsy (3 papers, 2024 to 2026). A brain disorder characterized by episodes of abnormally increased neuronal discharge resulting in transient episodes of sensory or motor neurological dysfunction, or psychic dysfunction. "In this study, we furnish genetic evidence supporting a worldwide as well as a regional link between lipid-lowering drugs such as HMGCR and PCSK9 inhibitors and epilepsy." (PMID 38523609, 2024). "Statins and PCSK9 inhibitors appear protective against epilepsy and several subtypes, whereas ezetimibe may increase susceptibility to certain subtypes." (PMID 41861198, 2026). "The drug target MR investigation suggests a possible link between reduced epilepsy vulnerability and HMGCR and PCSK9 inhibition." (PMID 38523609, 2024). "Through drug target Mendelian randomization, we systematically assessed the impact of lipid-lowering medications, including HMG-CoA reductase (HMGCR) inhibitors, proprotein convertase subtilisin/kexin type 9 (PCSK9) inhibitors, and Niemann-Pick C1-like 1 (NPC1L1) inhibitors, on epilepsy." (PMID 38523609, 2024).
esophageal squamous cell carcinoma (3 papers, 2021 to 2024). Esophageal squamous cell carcinoma (ESCC) is a type of esophageal carcinoma (EC) that can affect any part of the esophagus, but is usually located in the upper or middle third. "Tumors with dominant PCSK9 mutations included cervical adenocarcinoma, esophageal squamous cell carcinoma, esophagogastric adenocarcinoma, renal non-clear cell carcinoma, COAD, HNSC, KIRC, PAAD." (PMID 37860186, 2023). "In esophageal squamous cell carcinomas, PCSK9 was highly expressed in cancerous tissues compared with normal esophageal tissues, and its expression was associated with a poorer prognosis." (PMID 38611089, 2024). "In the immunohistochemical staining, the cytoplasm and nuclear compartments of esophageal squamous cell carcinoma tissue, but not the surrounding normal tissue, were predominantly stained with the PCSK9 antibody." (PMID 34504788, 2021). "Immunohistochemical staining demonstrated the expression of PCSK9 antigen in both the cytoplasm and nuclear compartments of esophageal squamous cell carcinoma tissue but not in normal tissue." (PMID 34504788, 2021).
Gestational Diabetes Mellitus (3 papers, 2022 to 2025). "The current study aimed to detect the expression of PCSK9 in pregnant women with gestational diabetes mellitus (GDM) and investigate the possible relationships between PCSK9 and related metabolic phenotypes in GDM." (PMID 35498417, 2022).
glioblastoma (3 papers, 2017 to 2024). The most malignant astrocytic tumor (WHO grade IV). "In this scenario, it is worth mentioning that inhibition of PCSK9 (evolocumab) is being tested in metastatic pancreatic cancer (NCT-04862260) and glioblastoma (NCT-04937413)." (PMID 38611089, 2024). "Cholesterol metabolism disruption, by combining PCSK9 inhibition with ezetimibe and a statin, is currently under investigation in patients with metastatic pancreatic cancers (NCT 04862260), while PCSK9 inhibition and its effect on MHC-I is being studied in patients with glioblastomas (NCT 04937413)." (PMID 36203122, 2022).
Graves’ orbitopathy (3 papers, 2020 to 2024). "In vitro studies showed that PCSK9 inhibition significantly reduced pro-inflammatory cytokines production, oxidative stress markers and adipocytes formation in Graves’ orbitopathy." (PMID 35323699, 2022). "However, elevated levels of PCSK9 have been found in patients with Graves’ orbitopathy and its concentration has positively correlated with autoantibodies against TSH receptor and clinical activity score." (PMID 35323699, 2022). "We sought to investigate the role of PCSK9 in the pathogenesis of Graves’ orbitopathy (GO) and whether it may be a legitimate target for treatment." (PMID 33488522, 2020).
hyperlipoproteinemia (3 papers, 2020 to 2023). An elevated concentration of lipoproteins. "Notably, individuals carrying the PCSK9 670G allele exhibited notably diminished hyperlipoproteinemia(a) frequencies, showcasing a dose-dependent relationship (p = 0.010)." (PMID 37834124, 2023). "Accordingly, a case report of a patient with HBV-related HCC and substantial type III hyperlipoproteinemia described high serum PCSK9 levels with PCSK9 mRNA levels being 4-fold higher in the tumor than in nontumor tissues." (PMID 35162992, 2022).
inflammatory bowel disease (3 papers, 2018 to 2025). A spectrum of small and large bowel inflammatory diseases of unknown etiology. "Along with those already mentioned, other top up-regulated DEGs such as Uck2, Krt23, Pcsk9, and S100a11 have also been associated with cancer or inflammatory bowel disease (IBD), likely reflecting their roles in cell proliferation or repair." (PMID 29339782, 2018). "Background/Objectives: Proprotein convertase subtilisin/kexin type 9 (PCSK9) regulates serum cholesterol levels and inflammation, both of which are dysregulated in inflammatory bowel disease (IBD)." (PMID 40265438, 2025).
lung diseases (3 papers, 2022 to 2024). "Despite the consistency of associations of genetic variants in PCSK9 and the risk of lung diseases in these two large biobanks and the underlying biological plausibility, there are several other factors to consider in interpreting these findings." (PMID 38198221, 2024). "Furthermore, low level of intracellular PCSK9 may be a risk factor for such lung diseases development." (PMID 39138259, 2024). "Focusing mainly on these three cell types, we were able to delineate the expression levels of PCSK9 in healthy and lung disease conditions by using similar number of cells in all conditions (∼ 3200 cells)." (PMID 39138259, 2024). "We suggest that higher levels of PCSK9 in BALF are to be considered as a risk factor for inflammatory exacerbation in lung diseases including fibrosis and COPD but intracellular PCSK9 may protect against development of lung disease." (PMID 39138259, 2024).
multiple sclerosis (3 papers, 2021 to 2025). A progressive autoimmune disorder affecting the central nervous system resulting in demyelination. "In a mouse model of multiple sclerosis, PCSK9 did not alter the progression of the disease or the associated immune responses." (PMID 37586604, 2023). "In experimental autoimmune encephalomyelitis, altering PCSK9 does not change clinical course or canonical immune readouts, and reviews of multiple sclerosis do not place PCSK9 among core disease mechanisms despite the central importance of lipid metabolism in myelin biology." (PMID 41002444, 2025).